Y_RNA (Y RNA )
Gene: Miscellaneous RNA gene on chromosome 6 (130,573,996 to 130,574,112, reverse strand). Ensembl gene ENSG00000202438.
Homologues: Orthologues: chimpanzee Y_RNA (99% identical), macaque Y_RNA (80% identical). Paralogues in human: Y_RNA (73% identical), RNY3 (72% identical), Y_RNA (72% identical), RNY3P1 (71% identical), Y_RNA (71% identical), Y_RNA (70% identical), Y_RNA (69% identical), Y_RNA (68% identical), RNY3P11 (68% identical), RNY3P14 (68% identical), RNY3P5 (68% identical), Y_RNA (67% identical), and 82 more.